LCN2 (lipocalin 2)
Diseases named in the same sentence as LCN2 in open-access papers (continued):
Sharing a sentence is not in itself a finding about the gene and the disease.
viral infection (27 papers, 2011 to 2026). "LCN2 is a multifaceted protein member of the adipocytokines with a well-characterized bacteriostatic role, and its association with viral infections has been described." (PMID 36613462, 2022). "In respiratory syncytial virus infection, overexpression of LCN2 was reported to be associated with more severe viral infection." (PMID 33242255, 2020). "The finding that poly I:C, an activator of TLR3 and RNA helicase signaling also induced Lcn2 gene expression in the C8 microglia indicates that additional innate signaling pathways associated with viral infection may also regulate the expression of the Lcn2 gene." (PMID 21943033, 2011). "In the realm of viral infections, Lcn2 exhibits a close correlation with disease severity in patients afflicted with influenza, displaying markedly elevated levels in severe cases compared to mild or moderate ones." (PMID 39180285, 2025). "At present, the role and exact molecular mechanism of LCN2 are still unclear and need to be further explored in severe viral infection." (PMID 35495713, 2022). "Overexpression of LCN2 in respiratory syncytial virus infection has been reported to be a very severe viral infection." (PMID 35284643, 2022). "LCN2 is a key regulator of inflammation during mycobacterial infection and deactivates macrophages during viral infection." (PMID 35019712, 2022). "Our study identifies LCN2 as an important modulator of antiviral immunity and suggests that LCN2 fine-tunes DC activity during homeostasis and to prevent excessive T cell expansion and immunopathology during viral infections." (PMID 33905460, 2021). "Here, we aimed to examine the role of LCN2 as modulator of lung immunity in the context of homeostasis and viral infections." (PMID 33905460, 2021). "Post PCV2 infection, we identified 199 differentially expressed lncRNAs, which appear to modify genes associated with viral infection, such as SOD2, TNFAIP3, ARG1, SERPINB2, VLDLR, HSPA5, and LCN2." (PMID 30863688, 2019). "Hence, there was a robust positive correlation between the Lcn2 protein expression level in serum and the progression of disease in mice during viral infection." (PMID 39180285, 2025). "For instance, decreased LCN2 levels might identify patients at risk of exaggerated responses to inflammatory triggers such as viral infections, and, on the other hand, supraphysiological LCN2 levels might prevent proper function of the adaptive immune system." (PMID 33905460, 2021). "While we here focused on influenza infection, LCN2-regulated inflammation and immunopathology might also importantly influence the course of other viral infections." (PMID 33905460, 2021). "Therefore, the appropriate level of LCN2 possesses a protective role in mild virus infection." (PMID 35495713, 2022). "Our five genes included three genes overexpressed in bacterial infections (LCN2, PI3, and SLPI) and two overexpressed in viral infections (IFI27 and IFIT2)." (PMID 40843077, 2025). "Several genes in this group (CTSG, encoding the neutrophil serin protease Cathepsin G; DEAFA4, defensin alpha 4; LCN2, lipocalin 2; OLFM4, BPI and CD24), are known to be overexpressed in patients with severe viral infections, including COVID-197,14." (PMID 35181735, 2022). "In this study, we evaluated the lipocalin-2 (LIP2) and syndecan-4 (SYN4) levels in children who were hospitalized for radiologically confirmed CAP in order to differentiate bacterial from viral infection." (PMID 27439403, 2016). "Actually, we identified that LCN2, PI3, and SLPI were up-regulated in bacterial infections, and IFI27 and IFIT2 were up-regulated in viral infections in the study, which may be helpful in assisting with the diagnosis of B/V co-infection in children." (PMID 40843077, 2025). "Moreover, LCN2 was superior to other biomarkers, such WBC, CRP, procalcitonin or CD64 expression on neutrophils in the distinction between bacterial and viral infection." (PMID 37317134, 2023).
viral infection (continued). "Additionally, we also observed that some genes, such as LCN2 and LTF were predicted to be involved in the cell-mediated immune response, indicating they may be key genes to against viral infections." (PMID 36579334, 2022).
anemia (26 papers, 2012 to 2025). A reduction in the number of red blood cells, the amount of hemoglobin, and/or the volume of packed red blood cells. "Elevated plasma LCN2 was significantly associated with anemia in patients with systemic inflammation." (PMID 29765406, 2018). "Under inflammatory conditions, Lcn2 contributes to an iron-retentive response known as the anemia of inflammation, by promoting iron retention in macrophages." (PMID 30501637, 2018). "Thus, upon inflammation, the increase in hepcidin and lipocalin 2 levels promote hyposideremia and the development of anemia of inflammation upon long-term infection or chronic disease." (PMID 31108902, 2019). "In vivo, recombinant LCN2 retards recovery from the anemia in mice being affected by acute anemia." (PMID 29765406, 2018). "We further show that genetic deletion of LCN2 in mice that develop CKD prevented increases in bone and circulating levels of FGF23 and development of LVH, and improved lifespan, despite CKD and anemia of unchanged severity." (PMID 34334787, 2021). "At 23 weeks, Col4a3KO mice showed impaired kidney function, increased levels of kidney and serum LCN2, increased bone and serum FGF23, anemia, and left ventricular hypertrophy (LVH)." (PMID 34334787, 2021). "Deletion of Lcn2 in CKD mice did not improve kidney function or anemia but prevented the development of LVH and improved survival in association with marked reductions in serum FGF23." (PMID 34334787, 2021).
Anxiety (26 papers, 2012 to 2026). Intense feelings of nervousness, tension, or panic often arise in response to interpersonal stresses. "More importantly, since the improvement of anxiety symptoms was associated with decreased serum LCN2, its value as a clinical biomarker in evaluating antidepressant efficiency can be further appreciated." (PMID 38589429, 2024). "When the mice received fluoxetine treatment, peripheral and central LCN2 were both suppressed in association with the relief of anxiety-like behaviors." (PMID 38589429, 2024). "Significant behavioral differences between aging groups were observed in all the dimensions analyzed and, in mice deficient in LCN2, aging mainly reduced anxiety, while sustained depressive-like behavior observed at younger ages." (PMID 37168715, 2023). "Another study reported that LCN2‐deficient mice displayed more anxiety and depressive behavior as well as cognitive decline, and LCN2 has also been shown to mediate iron import into the brain." (PMID 33945675, 2021). "Mariusz and co-workers demonstrated that LCN2 was significantly upregulated in the mouse hippocampus after stress, which resulted in the loss of dendritic spines and regulation of neuronal excitability (as a result of reduced dendritic spine actin mobility), and increased anxiety." (PMID 34179014, 2021). "Behavioral assays also suggested the prevention of anxiety-like phenotypes in CRS mice with hepatic Lcn2 gene knockdown." (PMID 38589429, 2024). "Taken together, these results suggest the central role of liver-derived LCN2 in responding to stress, disrupting cortical neural activity, and leading to anxiety-like behaviors." (PMID 38589429, 2024). "In sum, evidence from surgical, pharmaceutical, and genetic manipulations demonstrated that the vagal efferent pathway mediates hepatic LCN2 biosynthesis under stress to induce anxiety-like phenotypes." (PMID 38589429, 2024). "Taken together, these results show that stress activates the DMX, which is involved in hepatic LCN2 biosynthesis probably via vagal efferent pathways, further disrupting mPFC functions and resulting in anxiety-like behaviors." (PMID 38589429, 2024). "Next, we tested the specificity of LCN2 molecules within this vagal efferent modulation of anxiety-like behaviors." (PMID 38589429, 2024). "Such evidence formed a putative vagal-liver-cortex loop in which the brain stem nuclei transduced psychological stress into liver production of LCN2, which stimulated the mPFC to affect neural activity, resulting in anxiety-like behaviors." (PMID 38589429, 2024). "Using a mouse model of chronic restraint stress (CRS), circulating LCN2 was found to be related to stress-induced anxiety-like behaviour via modulation of neural activity in the medial prefrontal cortex (mPFC)." (PMID 38589429, 2024). "Here the authors identified liver-derived lipocalin 2 as a peripheral factor that elicits anxiety-like behaviours via modulating medial prefrontal neural activity." (PMID 38589429, 2024). "Although antibody treatment did not change the neuronal activity of the DMX, it did attenuate the blood LCN2 surge and block anxiety-like behaviors following chemogenetic activation." (PMID 38589429, 2024). "The elevated serum LCN2 further disrupted normal neural activity in the mPFC, leading to anxiety-like behaviors." (PMID 38589429, 2024). "In the mPFC, however, the local over-expression of LCN2 effectively induced anxiety-like behaviors in naïve, unstressed mice but did not alter the general locomotor behaviors, highlighting the anxiogenic role of LCN2 preferentially in the mPFC." (PMID 38589429, 2024). "A 14-day persistent infusion of Ab-LCN2 markedly decreased local protein levels in the mPFC even with viral-mediated over-expression and effectively prevented the occurrence of anxiety-like behaviors." (PMID 38589429, 2024).
Anxiety (continued). "As function evidence, the blue light stimulation in the DMX effectively elevated hepatic production of LCN2 into blood circulation, resulting in anxiety-like behaviors in naïve mice." (PMID 38589429, 2024). "In this test, a decreased ratio time dark/light was observed in older LCN2-null animals, when compared to younger mice (18- < 2-months, p = 0.002), confirming the reduction in anxiety by aging in LCN2-null mice." (PMID 37168715, 2023). "We show that CORT differentially affected cell proliferation and survival in Wt and LCN2-null mice, and glucocorticoids-driven anxiety and poor contextual discriminative behaviors were inexistent in the absence of LCN2." (PMID 37958520, 2023). "Together, our data reveal that an LCN2 absence blocks glucocorticoids-driven anxiety and cognitive function, as it prevents CORT-promoted hippocampal neurogenesis decline." (PMID 37958520, 2023). "The exception concerned the anxiety domain, since the time spent in the open arms by LCN2-null mice increased with aging." (PMID 37168715, 2023). "Certainly, we must consider that the effects of stress largely depend on the stress duration and paradigm used, as others have reported LCN2-null mice to present enhanced stress-induced anxiety after restraint stress." (PMID 37958520, 2023). "In our previous study, we demonstrated that management of lipocalin-2 reduced astrocyte activation and improved cognitive functions, social avoidance, and anxiety-like behaviors." (PMID 36558562, 2022). "In one such study, Lcn2 KO mice displayed increased anxiety and depressive-like behaviors and mild spatial reference memory impairments." (PMID 33613327, 2021). "This study suggests that the treatment of EA at Baihui (GV 20) and Dazhui (GV 14) acupoints improves RSDS-induced social avoidance, anxiety-like behaviors, astrocyte activation, and lipocalin 2 expression." (PMID 34565419, 2021). "We recently reported that increased lipocalin-2 in the CNS contributes to astrogliosis as well as cognitive and behavioral dysfunction, and increased lipocalin-2 in the brain impaired cognitive function and evoked anxiety-like behaviors in animal models." (PMID 35010945, 2021). "This, in turn, increased the generation of newborn neurons, and contributed to partially reduce anxiety and improve contextual discrimination in LCN2-null mice." (PMID 30733506, 2019). "Together, our data reveals that voluntary exercise partially rescues LCN2-null mice impaired anxiety but it completely reverted contextual discriminatory behavior, possibly through its pro-neurogenic effects." (PMID 30733506, 2019). "Here we identified the involvement of LCN2 in emotion and cognition as 10 weeks old male LCN2-null mice displayed increased anxiety and depressive-like behaviors and mild spatial reference memory impairments." (PMID 23908604, 2013). "In addition to our findings in the hippocampus, the evidence presented here suggests that the basolateral amygdala of lipocalin-2 deficient mice may also contribute to increased anxiety-like behaviour through aberrant dendritic spine plasticity and higher neuronal excitability." (PMID 23593384, 2013). "Disruption of genes involved in spine formation can also cause deficits in anxiety behaviour and it has been shown that Lipocalin-2 (Lcn2) regulates stress-induced anxiety in mice via changes in spine morphology and density." (PMID 23055942, 2012). "Behavioral tests showed that peripheral LCN2 may enter the brain and induced anxiety-like behaviors in naïve, stress-free mice." (PMID 38589429, 2024). "To better mimic the central effect of LCN2, we developed an adeno-associated virus (AAV) vector expressing LCN2 under the universal promoter (EF1α) and separately injected it into 3 regions closely related to anxiety: the hippocampus, amygdala and mPFC." (PMID 38589429, 2024).
Anxiety (continued). "Interestingly, individual LCN2 concentrations were inversely correlated with the Hamilton Anxiety Scale (HAMA), and their LCN2 levels were markedly decreased in all of 13 patients after 3-month treatment." (PMID 38589429, 2024). "Noticeably, Lcn2 has been shown to be up-regulated in the hippocampus after restraint stress to control neuronal excitability and anxiety behavior, and, in physiological conditions, LCN2-null mice present mood and cognitive alterations and impaired cell genesis." (PMID 37958520, 2023). "It is well known that increased anxiety is an important feature of depressive states, and the observed decreased anxiety, at least for the LCN2-null mice, may account to the reduced behavioral despair observed in the FST by aged mice." (PMID 37168715, 2023). "In addition, aging also induced a reduction in the anxiety state presented by LCN2-null mice at 2-months of age." (PMID 37168715, 2023). "In addition, intracerebroventricular injection of mouse recombinant lipocalin 2 protein in the lateral ventricles provoked social avoidance, anxiety-like behaviors, and the activation of astrocytes in the hippocampus." (PMID 34565419, 2021). "Furthermore, studies using Lcn2 knockout mice suggest an important role for LCN2 in several biobehavioral responses, including cognition, emotion, anxiety, and feeding behavior." (PMID 33613327, 2021). "Importantly, this increase in neurogenesis potentially provided the plasticity required to partially reduce anxiety and restore contextual fear discrimination in LCN2-null mice." (PMID 30733506, 2019). "One of the genes, lipocallin-2 (Lcn2) which we found as highly expressed in defeated mice, has already been reported to be upregulated in mouse hippocampus in psychosocial stress and involved in neuronal excitability and anxiety in response to stress." (PMID 31440139, 2019). "We observed that running, by counteracting oxidative stress in NSCs, reverses LCN2-null mice defective hippocampal neurogenesis, as it promotes NSCs cell cycle progression and maturation, resulting in a partial reduction in anxiety and improved contextual behaviour." (PMID 30733506, 2019). "Region-specific effects of Lcn-2 in the amygdala provide a novel mechanism for stress-induced neuroplasticity and may contribute to anxiety behaviour." (PMID 23593384, 2013). "As such, performing microarray analysis in control and stressed lipocalin-2 knockouts and comparing to our own data could help identify co-regulated transcripts which are key in regulating responses to stress and anxiety." (PMID 23593384, 2013). "In accordance, LCN2-null mice are reported to have stress-induced anxiety." (PMID 23908604, 2013). "Therefore, peripheral LCN2 potentially contributes to anxiety-like behaviors under stress." (PMID 38589429, 2024). "Our recent findings also showed that increased levels of lipocalin-2 in the CNS may contribute to astrogliosis and cognitive and behavioral changes, and exogenous lipocalin-2 in the brain impaired cognitive function and evoked anxiety-like behaviors in the animal models." (PMID 35010945, 2021). "Our findings suggest that EA stimulation at the Baihui (GV 20) and Dazhui (GV 14) acupoints effectively improves RSDS-elicited social avoidance and anxiety-like behaviors, and upregulation of lipocalin 2 in the brain may be an important biomarker for the development of PTSD-related symptoms." (PMID 34565419, 2021). "In a later extension of their study, the impaired hippocampal neurogenesis observed in Lcn2 KO mice was relieved by voluntary running, which counteracted oxidative stress and promoted cell cycling of neural stem cells, resulting in the partial reduction of anxiety and improved contextual behavior." (PMID 33613327, 2021). "In the current study, we first identified elevated serum LCN2 levels in anxiety disorder patients and chronic restraint stress (CRS) model mice with anxiety-like behaviors." (PMID 38589429, 2024).